HBM (hemoglobin subunit mu)
Synonyms: HBAP2; HBK
Tractability: No criterion of Open Targets' tractability assessment is met for any kind of drug.
Gene: Protein-coding gene on chromosome 16 (153,892 to 166,764, forward strand). Ensembl gene ENSG00000206177.
Gene Ontology:
Molecular function: protein binding; heme binding; oxygen carrier activity; oxygen binding
Biological process: erythrocyte development; oxygen transport
Cellular component: haptoglobin-hemoglobin complex; hemoglobin complex
Genetic constraint (gnomAD): Loss-of-function variants: 9 observed, 10.88 expected, observed/expected ratio (o/e) 0.83, 90% interval 0.5 to 1.44. The upper end of that interval is the gene's LOEUF score, 1.44, which puts it in group 5 of 6, group 1 being the genes least tolerant of losing a copy. Missense variants: 214 observed, 175.01 expected, observed/expected ratio (o/e) 1.22, 90% interval 1.09 to 1.37. Synonymous variants: 100 observed, 86.17 expected, observed/expected ratio (o/e) 1.16, 90% interval 0.99 to 1.37.
Homologues: Orthologues: chimpanzee HBM (98% identical), macaque HBM (96% identical), dog HBM (88% identical), pig HBM (83% identical), Drosophila melanogaster glob1 (20% identical), Caenorhabditis elegans glb-14 (19% identical), Caenorhabditis elegans glb-34 (16% identical). Paralogues in human: HBZ (48% identical), HBA1 (45% identical), HBA2 (45% identical), HBQ1 (41% identical), HBE1 (37% identical), HBD (36% identical), HBG1 (35% identical), HBG2 (35% identical), HBB (34% identical), CYGB (28% identical), MB (24% identical).
Diseases named in the same sentence as HBM in open-access papers:
HBM is named in the same sentence as 9 diseases in open-access papers, as found by Europe PMC text mining. Sharing a sentence is not in itself a finding about the gene and the disease. The quoted sentences say what the papers report.
anemia (3 papers, 2020 to 2023). A reduction in the number of red blood cells, the amount of hemoglobin, and/or the volume of packed red blood cells. "Interestingly, two of the six modules (network modules 1 and 4) contained genes that code for proteins expressed in erythrocytes or other blood components (HBM, RHD, GYPA, GYPC, CA1), or have been implicated in blood-associated diseases like anemia (GYPA)." (PMID 32728112, 2020).
methemoglobinemia (2 papers, 2008 to 2024). An inherited or acquired condition characterized by abnormally increased levels of methemoglobin in the blood. "Another less common form of congenital methemoglobinemia occurs in individuals who have an aberrant form of hemoblogin (HbM), where the reduced ferrous ion is destabilized and is more easily oxidized to a ferric ion." (PMID 18215265, 2008).
osteoporosis (1 paper, 2020). A condition of reduced bone mass, with decreased cortical thickness and a decrease in the number and size of the trabeculae of cancellous bone (but normal chemical composition), resulting in increased fracture incidence. "Our findings support SMAD9 as a novel HBM gene and a potential novel osteoanabolic target for osteoporosis therapeutics." (PMID 31525280, 2020).
α-thalassemia (1 paper, 2025). "This region includes HBM, HBA2, HBA1 and HBQ1, which is associated with the pathogenesis of α-thalassemia." (PMID 41444645, 2025).
tumor (2 papers, 2021 to 2024). "This tumor is usually positive for Pax8, melanocytic markers (melan-A and HBM-45), and cathepsin-K." (PMID 39502747, 2024). "Because this is such an aggressive tumor model, we did not test the gain-of-function VP16 HBM mutant." (PMID 33416496, 2021).
HBM also shares sentences with these, for which no sentence is quoted: malaria (2 papers); hereditary methemoglobinemia (1); lung carcinoma (1); tick-borne diseases (1).